IL4 (interleukin 4)
Diseases named in the same sentence as IL4 in open-access papers (continued):
Sharing a sentence is not in itself a finding about the gene and the disease.
asthma (continued). "Driven by T helper 2 (Th2) cells and T2 cytokines, such as interleukin 4 (IL-4), IL-5, and IL-13, the T2-high asthma endotype involves eosinophils, which may provide partial protection against COVID-19 by suppressing T1 inflammatory responses and cytokine storms." (PMID 40149651, 2025). "Approximately 50–80% of patients with asthma present with a T2-high endotype, which may be allergic (IgE-mediated) or eosinophilic (IL-5-mediated), and is driven by cytokines such as interleukin-4 (IL-4), IL-5, and IL-13." (PMID 41405763, 2025). "In asthma, there were variations in ACE2 expression due to different asthma endotypes which can influence COVID-19 susceptibility, with IL-17 potentially upregulating ACE2 expression, while IL-4 and IL-13 may downregulate it." (PMID 38899005, 2024). "Notably, treatment with BXM significantly ameliorated asthma symptoms, including less lung inflammation, mucus secretion, and the generation of Th2 cytokines (IL-5, IL-13, and IL-4), which were dramatically attenuated by anti-VISTA monoclonal antibody treatment." (PMID 38340268, 2024). "Thus, in contrast to the Type 2 (T2 or eosinophilic) type of asthma which was mediated by IL-4, IL-5, and IL-13, the profile of the inflammatory mediators with high levels of IL-6, CXCL8, and IFNγ after TLR stimulation mirrored that of the non-T2 endotype of asthma." (PMID 39614276, 2024). "In addition, asthma is related to the airways’ persistent inflammation, and for example, tumor necrosis factor-α, IL-4, transforming growth factor-β, IL-6, and vascular endothelial cell growth factor are all involved in the inflammatory response of asthmatic lungs as well as airway remodeling." (PMID 38594768, 2024). "Moreover, in a murine model of asthma, CBD-X administration significantly downregulated key asthma markers such as IgE and pro-asthmatic cytokines IL-4, IL-5, and IL-13 in both blood and lung tissues, and inhibited the migration of leukocytes, eosinophils, and neutrophils to lung tissues." (PMID 39459021, 2024). "Furthermore, IL-4 and IL-13 play a critical role in asthma pathobiology." (PMID 39188724, 2024). "Moreover, a study with IL-4- and IL-13-treated macrophages stimulated with IL-33 (an asthma cellular model) induced an increase in the expression of miR-155-5p, along with an increase in inflammatory mediators (Ccl3, Ccl5, Ccl17, Ccl24, and Il1b) compared to macrophages without pretreatment." (PMID 38337625, 2024). "In this sense, asthma is a respiratory disease characterized by a chronic inflammation including the activation of the Th2 cell response to allergens, and is often found to have elevated levels of inflammatory cytokines including IL-4, IL-5, IL-13, TNF-α, and IL-1β, among others." (PMID 38792145, 2024). "Similarly to asthma, mast cells, Th2 cells, basophils, and epithelial cells synthesize and release cytokines and chemokines (IL-3, IL-4, IL-5, IL-10, IL-13, GM-CSF, and RANTES), which are responsible for sustaining allergic inflammation and the associated oxidative/nitrosative stress." (PMID 39703514, 2024). "The highest enriched pathway, positive regulation of IL-4 production, along with TGFBI (transforming growth factor beta induced), suggest that the V stimulus promoted immune-suppressive activity, which in mammals is associated with Th9 cells linked to allergy in asthma and autoimmunity." (PMID 39015564, 2024). "Additionally, anti-IL-4 has been shown to be safe when administered to patients with asthma, implying that it could be applied in the treatment of thrombocytopenia." (PMID 36695938, 2023). "In addition to IL‐4 and IL‐5, granulocyte‐macrophage colony‐stimulating factor (GM‐CSF) is also an important mediator driving eosinophil accumulation in airway inflammation in asthma." (PMID 37773696, 2023).
asthma (continued). "Likewise, stamen extract of Mesua ferrea L. (Calophyllaceae) from the Calophyllaceae family and root extract of Clerodendrum serratum of the genus Clerodendrum is reported to ameliorate allergic asthma through the modulation of few asthma-associated cytokines like TNF-α, IL-5, and IL-4." (PMID 37251328, 2023). "Th2 cells, defined by the production of IL-4 and the expression of the transcription factor GATA-3, are involved in humoral immunity and eliminate extracellular pathogens but are associated with the development of allergic diseases, such as allergic rhinitis and asthma." (PMID 38139314, 2023). "Interestingly, either the overexpression of Nr1d1 or the treatment with its ligand (SR9011) protected mice against lung inflammation in an asthma model (as shown by lung histology, reduced histological scores, IL-4-, IL-5-, and IL-13-levels, as well as reduced GATA3 expression) [37••]." (PMID 36520269, 2023). "Furthermore, in patients with T2-high asthma, such a complex process may result in IgE, IL-13, IL-4, IL-5, and eosinophil responses, covering more than 50% of asthma endotypes." (PMID 38203353, 2023). "In the present study, we suspect that monoclonal antibodies targeting IL-4 and/or IL-13 may inhibit central processes that improve outcomes in patients with or without mixed phenotypes that may have a reduced capacity for response to baseline asthma therapies." (PMID 37901346, 2023). "In conclusion, inhibition of IL-4 and IL-13, and to a lesser degree inhibition of IL-13 alone, may benefit patients with T2 high asthma, such as those with elevated FeNO levels, elevated blood eosinophils (≥300 cells/μL) or sputum eosinophils (≥3%), and/or elevated periostin." (PMID 40980110, 2023). "IL-4 and IL-13 were found to downregulate polymeric immunoglobulin receptor (pIgR) at the site of IgA binding on airway epithelial cells, suggesting that IgA levels may be reduced in asthma." (PMID 37445635, 2023). "In addition, patients with anti-IL-4 therapy improved asthma control at 24 weeks." (PMID 37259416, 2023). "Although ADNP has not been identified as a common factor in asthma susceptibility, unlike IL-4, IL-5, and IL-13, it was reported among a subset of genes that were differentially expressed by CD4+ lymphocytes and that predicted more atopic from less atopic children." (PMID 37285842, 2023). "Numerous previous studies have shown that eosinophilic asthma is mainly characterized by IgE and Th2 cytokines (IL-4, IL-5, etc.), whereas neutrophil asthma is mainly characterized by Th17 cytokines (IL-17, IL-6, etc.), which are involved in the development of steroid-resistant asthma." (PMID 36081945, 2022). "Additionally, there are other cytokines which could be targeted for asthma, namely IL-4 and IL-13 and whilst there has been some study in this area, only one IL-4 inhibitor has been approved for asthma treatment (Dupilumab)." (PMID 36232470, 2022). "Therefore, in this review, the IL-4/IL-13 signaling pathways and therapeutic monoclonal antibodies targeting each cytokine or their receptors, as well as dual IL-4/IL-13 blockade, in both AR and asthma are presented and discussed." (PMID 35663523, 2022). "In addition, studies have shown that IL-4 can modify the activation of nuclear factor κB (NF-κB) induced by other agents, and NF-κB also plays an important role in the pathogenesis of IL-13-induced tissue damage in asthma." (PMID 35281601, 2022). "For instance, IL-4 may stimulate pIgR expression in Calu-3 cell line cultures, while it inhibits pIgR expression in primary airway epithelial cells, contributing to pIgR downregulation found in the airway epithelium of asthma patients." (PMID 35456002, 2022). "Besides, piRNAs are shown to regulate Th2 cell development by downregulating IL-4, thus inhibiting allergic inflammation and asthma and have specific binding partners in synovial fibroblasts, suggesting its role in inflammatory processes like Rheumatoid Arthritis." (PMID 34965192, 2022).
asthma (continued). "Therefore, we can hypothesize that asthma is involved in the persistence of OD because of higher levels of circulating IL-4." (PMID 35888019, 2022). "Genetic polymorphisms in genes including alarmin cytokines (TSLP and IL-33) type 2 cytokines (IL-4, IL-13) and other inflammatory-related proteins (HLA, ADAM33), and vitamin D receptor have been shown to enhance, or reduce, the risk and severity of asthma in individuals." (PMID 36292755, 2022). "Furthermore, earlier studies have revealed an IL-4/STAT-6/Tfec/IL-4Rα positive feedback regulatory loop, in which Tfec transcribes IL-4Rα expression to promote M2 programming in macrophages, which was implicated in asthma pathogenesis." (PMID 35600600, 2022). "Since IL-4, IL-5, IL-10, IL-17, and IL-33 would not be measured in peripheral blood samples, we think it is not feasible to use these cytokines in clinical practice or in the research of the underlying mechanisms of the asthma phenotypes." (PMID 36326393, 2022). "Furthermore, curcumin-SLN reduced airway hyperresponsiveness and inflammatory cell infiltration, as well as the lower production of cytokines, including interleukin-4 and interleukin-13, indicating that it may be useful in the treatment of asthma." (PMID 35455087, 2022). "Thus, IL-4-responsive B cells play an important role in parasitic and asthma immune responses, but the role of B cell IL-4 per se, particularly in Type 2-mediated diseases, remains unclear." (PMID 35359977, 2022). "In asthma, Naive T lymphocytes are inadequately prepared to respond to inhaled aeroallergens with Th2 polarity, and upon restimulation by inhaled aeroallergens, they produce Th2 cytokines, IL-4, IL-5 and IL-13, that promote the pathological mechanisms of asthma." (PMID 35745177, 2022). "T2-high asthma is the most frequent endo/phenotype and is canonically marked by activation of type 2 helper (Th2) cells, type 2 innate lymphoid cells (ILC2s), mast cells, basophils, eosinophils and the production of type 2 cytokines (e.g., IL-3, IL-4, IL-5 and IL-13)." (PMID 34342773, 2022). "The three subfamilies of MAPKs have been involved in the pathogenesis of asthma, and JNK and P-38, in particular, are more closely associated with asthmatic airway inflammation, which can cause high expression of downstream factors such as IL-6, IL-1β, and IL-4 and IL-5, respectively." (PMID 36081945, 2022). "It was also reported that AUR could treat Th2 cells diseases such as asthma by inhibiting cell proliferation, decreasing the levels of cytokines (IL-4, IL-10, and IFN-γ) and NF-κB, and reducing nitric oxide (NO) production in phytohemagglutinin (PHA) stimulation." (PMID 35873643, 2022). "Notably, elevated IL-4 levels exert critical roles in asthma pathogenesis." (PMID 34836513, 2021). "Therefore, increasing IFN-γ/IL-4 or Th1/Th2 ratios could be considered a treatment approach for asthma." (PMID 34804178, 2021). "Finally, asthma-related Th2 cytokines such as IL-4, IL-5, and IL-13 can induce EGFR expression, while cytokines produced by activated eosinophils such as IL-3 and IL-5 can induce TGF-α production by epithelial cells and subsequently induce mucins production through EGFR signaling." (PMID 34248677, 2021). "Importantly, Glycyrrhiza reduced IL-4 production, improving the pathological features of asthma." (PMID 33884360, 2021). "In mice, ORMDL3 expression has been shown to be induced by allergen, IL-4 and IL-13 via STAT6 and in bronchial epithelial cells, overexpression of ORMDL3 has been shown to trigger activating transcription factor 6 (ATF6), which has also been implicated in airway remodeling in asthma." (PMID 35386986, 2021). "Therefore, increased levels of IL-13, IL-5, and IL-4 mediate the development of asthma." (PMID 34258300, 2021). "Thus, we speculate that combined blockade of IL-4 and IL-13 pathways is probably also required in order to efficiently reduce most features of asthma in human, as we observed here in mouse models with the IL-4 and IL-13 vaccines." (PMID 33976140, 2021).
asthma (continued). "This is consistent with our results suggesting that Fbp1 may be involved in the pathogenesis of asthma and that its elevated level in epithelial cells following ovalbumin challenge or IL‐4 or IL‐13 treatment may be a detrimental mechanism inducing injury in bronchial epithelial cells." (PMID 33960626, 2021). "The therapeutic interventions for different phenotypes include IL-17 antagonist (neutrophilic asthma), IL-4/13 antagonist and anti-IgE (allergen-induced asthma), corticosteroids and IL-5 antagonist (idiopathic eosinophilic asthma), and leukotriene antagonist (aspirin exacerbated asthma)." (PMID 33505494, 2021). "Therefore, IL-8 and IL-4 might be helpful in distinguishing between airway neutrophilia due to asthma or other pathological conditions." (PMID 34658882, 2021). "In the three treated groups of asthma and also, allergic rhinitis (Co-Q10 received groups, Co-Q10 and O-3 received groups, Co-Q10 and Mg-S received groups), reverse trend was found and significantly reduced IL-4, IL-5, IL-13, and restored the IFN-γ levels (P < 0.05)." (PMID 33743807, 2021). "Dupilumab, blocking IL-4 and Il-13 from binding to its receptors, was the first biologic approved for moderate to severe AD, and Omalizumb, anti- IgE monoclonal antibody, was the first biologic approved for the treatment of asthma in the Unated States and the European Union." (PMID 34911576, 2021). "Moreover, treatment with anti-TCRγδ antibody during the resolution of allergic response leads to prolonged eosinophilic and Th2 airway infiltration in an OVA-induced murine asthma model; similarly, it prevents the drop in IL-4 content, typically observed during resolution phase." (PMID 33661375, 2021). "Indeed, further studies that aim to assess the impact of different mAbs on specific asthma phenotypes according to the levels of IgE, IL-4, IL-5, and IL-13 may further optimize the efficacy of the current mAbs for the treatment of severe asthma." (PMID 34281184, 2021). "Further, among males with asthma, lower levels of TH1 cytokines were statistically significantly associated with higher levels of PFDA (IL-2 only), and higher levels of TH2 cytokines were statistically significantly associated with higher levels of PFOA (IL-4 and IL-5) and PFBS (IL-5 only)." (PMID 34712855, 2021). "Despite all these treatments, severe asthma can remain uncontrolled, thus requiring adjunctive biological therapies based on the use of monoclonal antibodies directed against immunoglobulins E (IgE), interleukin 5 (IL-5), IL-5 receptor, or interleukin-4 (IL-4) receptor." (PMID 33922072, 2021). "Similarly, IL-4+ γδ T lymphocytes are significantly increased in peripheral blood of asthmatic patients, compared to healthy control and in induced sputum (during asthma exacerbation) after short-term phytohemagglutinin stimulation." (PMID 33661375, 2021). "Besides, animal experiments showed that PT could treat asthma by regulating the expression of Mmp2 and il-4." (PMID 33133221, 2020). "Asthma is classically considered an IgE-mediated, lymphocyte T helper 2 (Th2)-associated pathology, with an allergic inflammatory infiltrate characterized by eosinophils, mast cells, and CD4+ T cells producing interleukin-4 (IL-4), IL-5, and IL-13 in the airways." (PMID 33324573, 2020). "The classical form of asthma is considered to be mediated by T helper cell type 2 (Th2) cells and is characterized by eosinophilic inflammation, immunoglobulin (Ig) E reactivity, and the predominance of Th2 cytokines such as interleukin (IL)-4, IL-5, and IL-13." (PMID 32580518, 2020). "A comparative study of (R)- and (S)-albuterol in a murine model of asthma revealed that although both compounds were able to reduce leukocyte infiltration and mucus production in the lung of allergic mice, only (R)-albuterol was found to inhibit the production of IL-4." (PMID 33287119, 2020).
asthma (continued). "First, the analysis was according to crude estimation of IL4 gene -589C/T polymorphism association with asthma susceptibility, regardless of the effect of confounding factors, like age, sex, environmental factors, and contribution of other genes in LD with IL4 gene." (PMID 33087044, 2020). "It is noteworthy that basophils are not only effector cells; actually, they may contribute to prime the Th2 adaptive response through early and significant production of IL-4, which is important to drive the T cells towards a type 2 phenotype in respiratory allergy/asthma." (PMID 32397396, 2020). "In addition to Th17 cells and Treg cells, many immunoregulatory cells, such as Th2 cells, Th1 cells, innate lymphoid cells, dendritic cells, natural killer T cells, and TH9 cells, and many endogenous cytokines related to asthma, such as IL4, IL-5, IL13, IL22, and IL25, are also involved." (PMID 32620122, 2020). "Pharmacological inhibition of TNF-α activity with the monoclonal antibody infliximab, suppressed IL-4 production, adhesion molecule expression, and eosinophil infiltration in a mouse experimental model of allergic rhinitis, the pathology of which is similar to asthma." (PMID 32194407, 2020). "Thus, ginseng can suppress IgE, IL-4, and IL-5 expression and Th2-to-Th1 cell ratio through the modulation of mast cell, basophil, and eosinophil activation, resulting in the attenuation of AD, allergic rhinitis, asthma, and pruritus." (PMID 32326081, 2020). "However, in the 1980s, the notion that asthma was nearly always atopic came into prominence, which lead to the use of asthma as an exemplar TH2-mediated atopic disease characterized by TH2 cytokines like IL-4, IL-5 and IL-13, eosinophilia and increased IgE production." (PMID 31120919, 2019). "Compared with helper T 2 (Th2) cytokines [IL-1β, IL-4, IL-5, and tumor necrosis factor-α (TNF-α)], helper T 1 (Th1) cytokines (IFN-γ and IL-12) are associated to antagonism of immunoglobulin E (IgE) synthesis and Th2 cell responses to restrain the progress of asthma." (PMID 31330806, 2019). "In an in vitro study, psoralen significantly suppressed T helper type 2 (Th2) cytokines such as IL-4, IL-5 and IL-13 and therefore regarded as a critical component of PF for its in vivo therapeutic effects on airway hyperresponsiveness and inflammation of asthma." (PMID 31827595, 2019). "Th2-cell derived cytokines including IL-4, IL-5, and IL-13 could contribute to long-term airway hyper-responsiveness and smooth muscle growth, which have significant impact on the decline of lung function and the development of asthma severity." (PMID 30691461, 2019). "Therefore, it is hypothesized that anti-IL-4 and anti-IL-13 therapies could decrease asthma exacerbation by inhibiting eosinophilic and airway inflammation." (PMID 31151443, 2019). "In regards to T lymphocytes, Th2 cells are considered one of the central players in asthma pathogenesis, as long as these cells participate in and coordinate the onset and progression of the inflammatory response in asthma through the release of cytokines, especially IL-4, IL-5, IL-9, and IL-13." (PMID 31019244, 2019). "Many studies confirmed that a broad spectrum of inflammatory mediators, such as IL-4, IL-5, and IL-13, synthesized and released by activated inflammatory cells, particularly Th2 cells, eventually induce airway mucus hypersecretion which is essential for the pathogenesis of asthma." (PMID 31073274, 2019). "However, these Abs have not shown any favorable therapeutic benefits in clinical trials for asthma, suggesting that blocking IL-4 or IL-13 alone might be insufficient because of the redundancy in their signaling pathways." (PMID 31123339, 2019). "The evidence of IL-25-mediated Th2 cell differentiation, increase in production of IL-4, IL-5, and IL-13, elevated IgE and IgG levels, eosinophil infiltration, goblet cell hyperplasia and mucus hypersecretion, provided the proof for the role of IL-25 into asthma pathogenesis." (PMID 31355170, 2019).